CD4 (CD4 molecule)
Diseases named in the same sentence as CD4 in open-access papers (continued):
Sharing a sentence is not in itself a finding about the gene and the disease.
lupus (continued). "We also detected increased DNA methylation after MTX treatment in CD4+ memory T cells at a CpG located in the WDFY4 gene, which is a gene reported to harbour SNPs associated with several rheumatic diseases, i.e. systemic lupus erythematosus, JIA and RA." (PMID 34867944, 2021). "Dysregulations in the differentiation of CD4+-regulatory-T-cells (Tregs) and CD4+-responder-T-cells (Tresps) are involved in the development of active systemic lupus erythematosus (SLE)." (PMID 34502409, 2021). "Others have shown increased numbers of CD4+CD69+ T cells with altered expression of interleukins and suggested a correlation with loss of self-tolerance in lupus mice." (PMID 34733276, 2021). "Demethylation of specific regulatory elements was found to induce perforin overexpression in CD4+ T cells from lupus patients." (PMID 34445118, 2021). "A series of elegant studies from Dr. Richardson’s group established the significant contribution of CD4+ T cell DNA hypomethylation to lupus." (PMID 34062726, 2021). "This study strongly suggests the vital contribution of global DNA hypomethylation in CD4+ T cells to lupus." (PMID 34062726, 2021). "For example, CD4+ T cells are hyperactive in systemic lupus erythematosus (SLE), and inhibiting glycolysis as well as the mitochondrial metabolism improved the outcome in an animal model." (PMID 33483502, 2021). "4MU also reduced infiltration of T cells into the kidneys and reduced the total number of CD4+IFNG+ cells in the spleens of lupus prone MRL/lpr mice." (PMID 34665782, 2021). "The hypomethylation of IFN-related genes such as IFI44L and BST2 was correlated with the overexpression of these two genes in total CD4+ T cells from lupus patients." (PMID 34062726, 2021). "Our study is based on the lupus-prone mouse model and support the therapeutic value of enhancing CD4+ T cell senescence in lupus mice via miR-199a-5p agomir." (PMID 33391511, 2021). "Collectively these data demonstrate that lupus patients have reduced percentages of both CD4+ and CD8+ Tregs." (PMID 33746959, 2021). "T We showed that D-mannose alleviated CD4+ T cell activation, expanded the frequency of Treg cells, restrained DC activation and ameliorated lupus phenotypes." (PMID 33402096, 2021). "We prove the significant changes of senescence markers in splenic CD4+ T cells of MRL/lpr mice and then demonstrate that hUC-MSCs rescue lupus phenotype with induction of CD4+ T cell senescence." (PMID 33391511, 2021). "In fact, these miRNAs were found overexpressed in CD4 T-cells from females affected by Systemic Lupus Erythematosus, and this mechanism was proposed as a contributing factor to the differential predisposition to this autoimmune condition." (PMID 34575659, 2021). "CD4+ T cells from lupus patients show enhanced levels of mTOR activation which has been mechanistically linked with the disease process." (PMID 33968025, 2021). "In the Lupus study, it was determined that anti-4-1BB treatment induced CD4+ T-cell anergy, and thus blocked T-cell-dependent humoral responses." (PMID 34282763, 2021). "Twin discordance in SLE is attributed to differences in DNA methylation, and enhanced expression of inflammatory genes in lupus CD4+ T cells is attributed to global hypomethylation." (PMID 34019642, 2021). "Lupus CD4+ T cells also present a skewed metabolic program that is directly associated with these immune dysregulations." (PMID 33402096, 2021). "Studies in lupus-prone New Zealand Black × New Zealand White (NZB/W) F1 mice revealed that the ratio of CD4+ Foxp3+ Tregs to CD4+ Foxp3− conventional T cells declined in lymphoid organs of these animals." (PMID 33496881, 2021). "CD4+, CD8+, and CD4−CD8− T lymphocytes promote a pro-inflammatory environment conducive to lupus pathogenesis and generation of pathogenic anti-DNA Ig secreting B cells." (PMID 33737712, 2021).
lupus (continued). "In particular, neutrophils can contribute to excess serum BAFF levels, through which they have been demonstrated to promote CD4+ T-cell and B-cell responses and enhance CD4+ T-cell proliferation and IFNγ secretion in lupus-prone mice." (PMID 34211466, 2021). "For example, X-linked miRNAs, including miR-188, miR-421, miR-503, let-7f-2, and miR-98, were found to be upregulated in CD4+ T cells from female lupus patients compared to male lupus patients potentially contributing to the sex difference in lupus." (PMID 34200989, 2021). "A high level of IFNα in the circulation of systemic lupus erythematosus patients was demonstrated to increase the capacity of monocytes to activate CD4+ T cells and to contribute to the break of tolerance." (PMID 34394090, 2021). "Expression of Sirt1 increased significantly in CD4+T cells from patients with active lupus which indicated increased Sirt1 expression is related to the development of SLE." (PMID 33584646, 2020). "Along these lines, MS and systemic lupus erythematosus (SLE) patients show higher frequencies of autoreactive CD4+ TEM and lower CD4+ TCM in peripheral blood compared with healthy controls." (PMID 32106536, 2020). "Fundamentally different from RA T cells, CD4 T cells from lupus patients and lupus-prone mice display high demand for glucose and depend on rapid production of ATP, requiring both mitochondrial activity and cytoplasmic glycolysis." (PMID 32477606, 2020). "CD4+ T cells from lupus patients have higher expression of IL-17 and SOCS3 than healthy controls, with positive correlation between IL-17 levels and SOCS3 expression." (PMID 33271810, 2020). "A significant increase of CD40L+ CD4+ T cells in the peripheral blood mononuclear cells (PBMCs) of patients with active lupus was detected." (PMID 33297945, 2020). "Systemic lupus erythematosus (SLE) is a prototypic systemic autoimmune disease characterized by abundant autoreactive CD4+ T cells, excessive autoantibody production, and immune complex deposition, with highly heterogeneous clinical manifestations." (PMID 32059488, 2020). "To understand the role of increased EGR2 in the context of lupus CD4+ T cells, we transfected splenocytes from MRL and MRL-lpr mice at 14–15 weeks-of age with specific EGR2 Dicer substrate siRNA (DsiRNA) to block EGR2 expression." (PMID 32646370, 2020). "Our in vitro data suggest a positive role of EGR2 in the regulation of Th1 differentiation and IFNγ production in lupus effector CD4+ T cells." (PMID 32646370, 2020). "In the search for anti-renal autoreactivity in human lupus nephritis, we stimulated blood-derived CD4+ T cells from patients with systemic lupus erythematosus with various kidney lysates." (PMID 33277543, 2020). "Finally, EZH2-mediated epigenetic dysregulation in naïve CD4+ T cells from SLE patients that are associated with increased disease activity suggest a role for EZH2 overexpression in lupus flares." (PMID 32395334, 2020). "Enhancer of zeste homolog 2 (EZH2), an epigenetic modulator important to T cell activation and differentiation, is over-activated in lupus CD4+ T cells." (PMID 32308657, 2020). "The murine bm12 model of lupus-like chronic graft versus host disease (cGVHD) was induced by intra-peritoneal injection of negatively isolated allogeneic CD4+ T cells." (PMID 32503684, 2020). "Bioinformatics analysis showed that these dys-acetylated peaks are involved in the regulation of cellular metabolism and several important immune and inflammatory pathways in lupus CD4+ T cells." (PMID 32984334, 2020).
lupus (continued). "We cannot exclude the possibility that high-salt intake affects the functional activity of CD4+ Foxp3+ Treg cells in our lupus model." (PMID 32296043, 2020). "In systemic lupus erythematosus, vitamin D induces reconstruction of the balance between B and T cells through stimulating an increase in CD4+ T cells and a decrease of memory B cells and anti-DNA antibodies." (PMID 33396346, 2020). "Our study identified novel dysregulated ac4C mRNAs associated with critical immune and inflammatory responses, that have translational potential in lupus CD4+ T cells." (PMID 32984334, 2020). "In active lupus patients or NZBxSWR mice, CD4+ as well as dnT cells augment the production of anti-dsDNA antibodies when they are co-cultured with oligoclonal autoreactive B cells." (PMID 32849532, 2020). "Activation of mTORC1 in CD4+ T cells has also been reported in a lupus mouse model as well as in SLE patients, suggesting that differentiation to Th1 and Th17 is enhanced by mTORC1 in wild-type and autoimmune mice." (PMID 33329581, 2020). "The proportion of Foxp3+ cells in CD4+IL-17A+ cells was significantly greater in patients with lupus than in those with IgA nephropathy." (PMID 32317002, 2020). "We found increased autophagy levels in naive CD4+ T lymphocytes of systemic lupus erythematosus (SLE) patients." (PMID 33424586, 2020). "To obtain the disease-related regulatory pathway of altered genes in lupus CD4+ T cells, we further investigated the functional enrichment of DEGs using Pathway maps, and Process Networks analyses." (PMID 32984334, 2020). "HMGB1 was found to drive DNA demethylation in CD4+ T cells of systemic lupus erythematosus (SLE) patients." (PMID 33029541, 2020). "Further, increased glycolysis was observed in naïve CD4+ T cells in lupus-prone mice, and was enhanced following T cell activation." (PMID 32395334, 2020). "Meanwhile, significantly lower mRNA acetyltransferase NAT10 expression was detected in lupus CD4+ T cells by RT-qPCR." (PMID 32984334, 2020). "In patients with rheumatoid arthritis and lupus, the percentage of circulating CD4+/CCR4+ T cells is significantly elevated relative to heathy controls." (PMID 32973504, 2020). "STAT1 levels in CD4+ T cells from lupus patients are higher than from rheumatoid arthritis patients and healthy subjects and positively correlate with disease activity, with highest levels in CD45RA-FOXP3hi-activated Tregs (aTregs)." (PMID 33271810, 2020). "Accordingly, in this study, we analyzed the expression of EGR2 in human lupus patients and in three different murine lupus models and detailed further the role EGR2 plays in the regulation of CD4+ T cell response and Th1 differentiation in lupus-prone mice." (PMID 32646370, 2020). "Naive CD4+ T cells in lupus undergo the proinflammatory shifts in epigenetics that favor T cell activation and effector T cell immune responses, which trigger lupus flares." (PMID 32308657, 2020). "MBZ was also shown to increase ERK activity in CD4+ T-cells from lupus patients with known defective ERK signalling." (PMID 32753665, 2020). "IL-21 has also been observed to engage mTOR, therefore suppressing autophagy, in CD4+ T cells leading to their dysfunction in the differentiation and effector functions in systemic lupus erythematosus." (PMID 32733448, 2020). "To understand further the function of elevated EGR2 in lupus CD4+ T cells, we inhibited EGR2 with a specific siRNA in vitro in splenocytes from MRL-lpr and control MRL mice at 15 weeks-of-age." (PMID 32646370, 2020). "In memory CD4+ T cells activated in asthma and the immature CD4+ T lymphocytes in systemic lupus erythematosus, the mRNA levels of differential genes were detected by reverse transcription analysis, and elevated PFDN5 mRNA levels were detected." (PMID 32699605, 2020). "In CD4+ T cells from lupus patients, low activity of DNMT1 has been observed after activation of AhR by UVB." (PMID 32899152, 2020).
lupus (continued). "Together, our data demonstrated a significant increase of EGR2 expression in CD4+ T cells of murine lupus cells when compared to their respective controls." (PMID 32646370, 2020). "We further demonstrated that EGR2 plays a differential role in a lupus context since it positively regulated Th1 differentiation and IFNγ production in CD4+ T cells from MRL-lpr lupus mice." (PMID 32646370, 2020). "We found that upregulated miR-126 promotes the expression of CD11a and CD70 in lupus CD4+ T cells via inhibiting DNMT1-mediated DNA methylation." (PMID 32308657, 2020). "In this study, using liquid chromatography-coupled tandem mass spectrometry (LC-MS/MS), we identified ac4C mRNA modification in lupus CD4+ T cells as a novel form of mRNA modification." (PMID 32984334, 2020). "Most of the studies on DNA methylation in lupus T cellshave been conducted on CD4+ T cells, whereas the current study examinedDNT cells and their precursor CD8+ Tcells." (PMID 33097564, 2020). "Previous reports have described a strong relationship between mRNA modification and gene expression, and hence, we sought to characterize the functional role of the ac4C modification in mRNA of lupus CD4+ T cells." (PMID 32984334, 2020). "More recent studies demonstrate that these cells comprise a distinct CD4+ T cell subset, making it a therapeutic target for the treatment of lupus flares." (PMID 30764520, 2019). "The present study confirms our previous observation that CD134+CD4+ T-cells are increased in the peripheral blood of patients with systemic lupus erythematosus as compared to HC." (PMID 31331400, 2019). "The present study demonstrates the altered cytokine pattern of CD134+ and PD-1+CD4+ effector T-cells in patients with systemic lupus erythematosus." (PMID 31331400, 2019). "In parallel and in line with previous findings in this lupus model, the frequency of IL-2 producing cells among splenic CD4+CD44hi T cells declined." (PMID 31614462, 2019). "The Pbx1-d dominant-negative isoform is more commonly expressed in CD4+ T cells from lupus patients than in those from healthy controls." (PMID 31440232, 2019). "After validating that CG-5 inhibits glucose uptake by CD4+ T cells, we examined its effect on CD4+ T cell activation and polarization in vitro as well as in lupus models." (PMID 31057554, 2019). "Hypomethylation of DNA tilts lupus CD4+ T cells towards autoreactivity, facilitating the production of pro-inflammatory chemokines and cytokines, autoantibodies and polyclonal expansion of autoreactive B cells via T-B cell crosstalk." (PMID 31575058, 2019). "In lupus CD4+ T cells, the up-regulated miR-21 can suppress the expression of DNA methyltransferase 1 and enhance DNA hypomethylation." (PMID 31163082, 2019). "We have recently observed that lupus CD4+ T cells display an increased 5-hmC level on whole genomic DNA compared with normal controls, with the enhanced expression of TET2 and TET3." (PMID 31611879, 2019). "Systemic lupus erythematosus (SLE) is an autoimmune disease in which autoreactive CD4+ T cells play an important role." (PMID 31412880, 2019). "In our former study, we found that HERV-E clone 4–1 mRNA expression was higher in lupus CD4+ T cells than in cells from healthy controls and the HERV-E clone 4–1 mRNA expression level was positively correlated with SLE disease activity." (PMID 31412880, 2019). "Partly due to the deficiency and inhibition of DNA methyltransferase 1 (Dnmt1), an enzyme crucial to maintain DNA methylation, the DNA of lupus CD4+ T cells is generally hypomethylated." (PMID 31575058, 2019). "In a murine lupus model, CD4+ and CD8+ T-cells from BTLA−/− MRL-lpr/lpr mice showed enhanced responses in α-CD3-induced proliferation as compared to BTLA+/+ MRL-lpr/lpr mice." (PMID 31514450, 2019). "The expression of two miRNAs—miR-21 and miR-148a, which promote CD4+ T cell hypomethylation, has been found to be upregulated in CD4+ T cells from both humans and mice with lupus." (PMID 31137759, 2019).
lupus (continued). "Special silencing of JMJD3 increased the enrichment of H3K27me3, suggesting that expression of JMJD3 in CD4+ T cells contributed to the progress in pathology of systemic lupus erythematosus." (PMID 31701394, 2019). "CD4+ T cells have numerous features of over-activated cellular metabolism in lupus patients and mouse models of the disease." (PMID 31057554, 2019). "The critical and complex role of epigenetic regulations in lupus T cells was demonstrated by showing that specifically demethylating either CD4+ or CD8+ T cells had beneficial effects while systemic demethylation worsened disease in MRL/lpr lupus-prone mice." (PMID 31001259, 2019). "HERV-E mRNA expression levels were found to be higher in lupus CD4+ T cells than in cells from healthy controls but the full contribution of HERV activity to SLE etiology is not known." (PMID 31481926, 2019). "The ratio of CD3+/CD19+ cells analyzed by flow cytometry was increased in all three lupus models indicating lymphocytes in the brains were T cell dominant with a similar CD4+/CD8+ ratio to controls." (PMID 31888754, 2019). "In humans and mice, senescent CD4+ T cells have been shown to play a role in the pathogenesis of rheumatoid arthritis and systemic lupus erythematosus, which are female-dominant systemic autoimmune diseases." (PMID 31596727, 2019). "Global DNA hypomethylation in CD4+ cells in systemic lupus erythematosus (SLE) was suggested to play a key role in the pathogenesis." (PMID 30816218, 2019). "It has been reported that the expression of RFX1 is decreased in the CD4+ T cells of lupus patients." (PMID 31737059, 2019). "It has been reported that the expression of RFX1 was decreased in the CD4+ T cells of lupus patients." (PMID 30857550, 2019). "Studies in lupus report an increased accumulation of effector/memory CD4+ T cells, Th17 cells, T follicular helper cells (TFH), γδ T cells, and double negative (DN) T cells in the blood, lymphoid tissue, and target organs." (PMID 29593732, 2018). "In a second study, they reported that ICs isolated from systemic lupus erythematosus patients interact with CD16 expressed by CD4+ T cells and induce Syk phosphorylation, providing a co-stimulatory signal to T cells in the absence of CD28 signal." (PMID 30555482, 2018). "CD4+ T cells from anti-dsDNA IgG-producing lupus-prone TC mice showed an increased expression of the early activation marker CD69, as well as an accumulation of effector memory T (TEM) and TFH cells as compared to B6 controls." (PMID 30348969, 2018). "The multi-organ dysfunctions produced by systemic lupus erythematosus generate a severe immune regulation disorder, with autoantibody overproduction, lupus nephritis, aberrant CD4+ T cell activation, and immune complex-mediated inflammation." (PMID 29740333, 2018). "For example, in MRL-lpr lupus models, CD4+ T cells show higher levels of AKT activation than in wild-type mice." (PMID 29884225, 2018). "Based on the therapeutic effects of the combination of metformin and 2-deoxyglucose (2DG) in lupus models that normalized the expansion of effector CD4+ T cells." (PMID 30233578, 2018). "Quercitrin, a glycoside formed from the flavonoid quercetin, diminished serum antibodies, reduced CD4+ T cell activation, and ameliorated lupus nephritis symptoms in a systemic lupus erythematosus mouse model." (PMID 29740333, 2018). "We have also shown that the combination of 2DG and metformin normalized the metabolism of lupus CD4+ T cells and reverse disease in multiple mouse models." (PMID 30233578, 2018). "Delivery of KN-93 targeted to CD4 T cells to lupus-prone MRL/lpr mice increased IL-2 levels in the serum, reduced IL-17 producing infiltrating cells in the kidneys and improved kidney function as measured by proteinuria." (PMID 30333818, 2018). "The 2DG plus metformin combination also reduced Bcl6 and PD-1 expression in total CD4+ T cells from these lupus strains." (PMID 30348969, 2018).